CTLA4 (cytotoxic T-lymphocyte associated protein 4)
Diseases named in the same sentence as CTLA4 in open-access papers (continued):
Sharing a sentence is not in itself a finding about the gene and the disease.
metastatic melanoma (continued). "The development of the cytotoxic T-lymphocyte-associated protein 4 inhibitor ipilimumab and its approval in 2011 for the treatment of metastatic melanoma has heralded a new era in immuno-oncology." (PMID 26288737, 2015). "Immune-checkpoint blockade, predominantly targeting cytotoxic T-lymphocyte-associated antigen 4 (CTLA-4) and PD-1/PD-L1-is currently the main focus of immunotherapies in metastatic melanoma." (PMID 24693430, 2014). "Another novel agent recently approved for the treatment of metastatic melanoma is ipilimumab, a fully human monoclonal antibody that blocks cytotoxic T-lymphocyte-associated antigen 4 (CTLA-4), an immune checkpoint molecule." (PMID 24499550, 2013). "The effects on cell signalling networks upon blockade of cytotoxic T lymphocyte-associated antigen-4 (CTLA4) using the monoclonal antibody tremelimumab were studied in peripheral blood mononuclear cell (PBMC) samples from patients with metastatic melanoma." (PMID 20856802, 2010). "Specific CTLA-4 polymorphisms have previously shown an association with response to CTLA-4 blockade in patients with metastatic melanoma and the development of autoimmunity." (PMID 21044351, 2010). "In a study by Sade-Feldman, the authors analyzed longitudinal tumor biopsies from 17 metastatic melanoma patients and observed that B2M deficiency was more prevalent in non-responder patients (29.4%) compared to responders (10%) treated with anti-CTLA-4 or anti-PD-1 therapy." (PMID 39273605, 2024). "Similarly, in metastatic melanoma, patients receiving cytotoxic T-lymphocyte-associated protein 4 (CTLA-4) inhibitors demonstrated clinical benefit when their tumors exhibited a high TNB." (PMID 39518080, 2024). "The first immune checkpoint inhibitor approved by FDA named lpilimumab that targets cytotoxic T-lymphocyte-associated protein 4 (CTLA-4) to potentiate the T cell-mediated antitumor immune response, have remarkably improved the overall survival of metastatic melanoma patients." (PMID 38177102, 2024). "Programmed cell death 1 receptor (PD-1) inhibition as monotherapy followed by Cytotoxic T-lymphocyte associated protein 4 (CTLA-4) inhibition in case of progression or as upfront double co-inhibition has drastically improved the survival outcomes of metastatic melanoma." (PMID 39435288, 2024). "Immune checkpoint inhibitors (ICIs), including programmed cell death protein 1 (PD-1) inhibitors, such as nivolumab, and cytotoxic T-lymphocyte-associated protein 4 (CTLA-4) inhibitors, such as ipilimumab, have revolutionized cancer treatment, particularly in metastatic melanoma." (PMID 39553010, 2024). "Immune checkpoint inhibitors (ICIs) such as nivolumab (a programmed cell death protein 1 {PD-1} inhibitor) and ipilimumab (a cytotoxic T-lymphocyte-associated protein 4 {CTLA-4} inhibitor) have significantly improved outcomes in various malignancies, including metastatic melanoma." (PMID 39553010, 2024). "Research studies have reported that the human intestinal microbiota structure is related to antitumor efficacy in metastatic melanoma patients exposed to anti- cytotoxic T-lymphocyte-associated protein 4 (CTLA-4) and anti-programmed cell death protein 1 (PD-1) monoclonal antibodies." (PMID 37627114, 2023). "Furthermore, composition of the gut microbiota seems to be linked with increased risk of anti-CTLA-4-stimulated colitis in patients with metastatic melanoma." (PMID 37627114, 2023). "In addition, antibodies of cytotoxic T-lymphocyte-associated protein 4 (CTLA-4), such as ipilimumab and tremelimumab, were confirmed useful in metastatic melanoma." (PMID 36793711, 2023). "Immunotherapy has been a breakthrough approach for metastatic melanoma, such as anti-cytotoxic T-lymphocyte-associated protein 4 (CTLA-4) and anti-programmed cell death protein 1 (PD-1) antibodies, which are based on the activation of the anticancer immune system." (PMID 35646893, 2022).
metastatic melanoma (continued). "Cytotoxic-T-lymphocyte-associated antigen-4 (CTLA-4) polymorphisms rs4553808, rs11571317, and rs231775 have been associated with response to therapy with ipilimumab for metastatic melanoma, and the CTLA-4 rs4553808 has also been correlated with higher incidence of endocrine side effects." (PMID 36230587, 2022). "As a breakthrough approach for metastatic melanoma, immunotherapy is based on the activation of the anticancer endogenous immune system, whose representative immune checkpoints are cytotoxic T-lymphocyte-associated protein 4 (CTLA-4) and programmed cell death protein 1 (PD-1)." (PMID 35186949, 2021). "Similarly, reduced IL-10 production was reportedly associated with the antitumor response and irAEs in metastatic melanoma patients treated with anti-CTLA-4 ticilimumab." (PMID 34732257, 2021). "In addition, TNB correlated with clinical benefit in patients with metastatic melanoma treated with cytotoxic T-lymphocyte-associated protein 4 (CTLA4) inhibitors." (PMID 33996601, 2021). "Interestingly, granzyme B-degraded type IV collagen fragments (C4G) associate with favorable anti-CTLA-4 treatment response in metastatic melanoma patients." (PMID 34121658, 2021). "Immune checkpoint inhibitors (ICIs) are commonly used in the therapeutic arsenal of metastatic melanoma, Merkel cell carcinoma and cutaneous squamous cell carcinoma due to their inhibitory effects on cytotoxic T-lymphocyte-associated protein 4 (anti-CTLA4) or anti-programmed death-1 (anti-PD1)." (PMID 33634154, 2021). "Specifically, we show that our matrix factorization approach (CoGAPS) detected a signature of intratumoral NK cell activation in anti-CTLA-4-treated mice which our transfer learning method (projectR) associated with positive clinical outcomes in metastatic melanoma." (PMID 34376232, 2021). "The Checkmate 067 trial investigated the impact of treatment of metastatic melanoma with the cytotoxic T-lymphocyte-associated protein 4 (CTLA-4) inhibitor ipilimumab alone, the programmed death-ligand 1 (PD-L1) inhibitor nivolumab alone, and combination therapy." (PMID 32455885, 2020). "Immune checkpoint inhibitors, in particular anti-PD-1 antibodies such as pembrolizumab and nivolumab and the combination of nivolumab with the anti-cytotoxic T-lymphocyte-associated protein 4 (CTLA-4) antibody ipilimumab can achieve long-term survival for patients with metastatic melanoma." (PMID 31947592, 2020). "There is also pre-clinical and clinical evidence that GM-CSF can be an effective immunostimulatory agent when being combined with anti-cytotoxic T lymphocyte-associated protein 4 (anti-CTLA-4) in patients with metastatic melanoma as well as in novel cancer immunotherapy approaches." (PMID 30769926, 2019). "Among immunotherapeutic approaches, antibodies targeting immune checkpoint inhibitors Programmed cell death protein 1 (PD-1) and cytotoxic T-lymphocyte-associated protein 4 (CTLA-4) are approved for treatment of metastatic melanoma and are in clinical trials for a variety of other cancers." (PMID 31614774, 2019). "Currently, the blockade of certain immune checkpoints such as the cytotoxic T-lymphocyte-associated protein 4 (CTLA-4) and programmed cell death-1 (PD-1) using checkpoint inhibitors is standard of care in patients with metastatic melanoma, especially with BRAF wild-type." (PMID 30828569, 2019). "Interestingly, it has been described that the mutational load of metastatic melanomas predicts a better response to CTLA-4 blockade." (PMID 29490700, 2018). "In the last decade, immune checkpoint blockades (ICBs) of targeting cytotoxic T-lymphocyte antigen-4 (CTLA-4), programmed death receptor-1 (PD-1) and its associated ligand (PD-L1) as monotherapy or combination therapy, have revolutionized the treatment of metastatic melanoma." (PMID 29793878, 2018).
metastatic melanoma (continued). "Despite the survival benefits of ipilimumab in metastatic melanoma, significant side effects of anti-CTLA-4 treatment include the associated immune-related adverse events (60% in patients treated with ipilimumab) which most commonly affect the gastrointestinal tract." (PMID 29211042, 2017). "Furthermore, therapeutic monoclonal antibodies against cytotoxic T-lymphocyte-associated antigen 4 (CTLA-4) and programmed cell death-1 to block inhibition signals received by T cells increased the long-term survival of metastatic melanoma patients." (PMID 27965469, 2017). "Ipilimumab, a monoclonal antibody that upregulates immune responses by targeting CTLA-4 (cytotoxic T-lymphocyte-associated protein 4), has been shown to prolong survival times in both previously treated and untreated metastatic melanoma patients when used in combination with other therapies." (PMID 26999120, 2016). "The cytotoxic T-lymphocyte-associated antigen-4 (CTLA-4) inhibitor ipilimumab has been authorized for use in advanced, metastatic melanoma in the United States and in the European Union—as in many other countries worldwide since—on basis of two pivotal phase III studies." (PMID 26541511, 2015). "Besides, ipilimumab was developed to block the cytotoxic T-lymphocyte-associated antigen 4 (CTLA-4) in patients with unresectable or metastatic melanoma." (PMID 23533766, 2013). "However, new hope has emerged for metastatic melanoma patients since the clinical approval of monoclonal antibodies developed against immune checkpoints, such as cytotoxic T lymphocyte-associated antigen 4 (CTLA-4) in 2011 and, subsequently, programmed cell death protein-1 (PD-1) in 2014." (PMID 40564098, 2025). "The approval of the anti–CTLA-4 antibody ipilimumab for metastatic melanoma in 2011 — a substantial milestone — was followed in 2014 with anti–PD-1 antibodies nivolumab and pembrolizumab to treat advanced or metastatic melanoma and as frontline therapy for high-risk patients in 2016." (PMID 39286978, 2024). "In light of the substantial toxicity associated with combined CTLA-4 and PD-1 blockade (ipilimumab and nivolumab), we assessed its efficacy and safety against anti-PD-1 monotherapy (nivolumab or pembrolizumab) in patients with metastatic melanoma under real-world conditions." (PMID 39516682, 2024). "To explore whether the IRG risk score could predict the response to immunotherapy, we applied the IRG risk score in the Van_allen dataset, the sequencing data from metastatic melanoma treatment with cytotoxic T lymphocyte-associated antigen-4 (CTLA-4) blockade." (PMID 37014331, 2023). "To explore whether the IIS risk score could predict immunotherapy response, we applied the IIS risk score to the Van_allen dataset, the sequencing data from metastatic melanoma treatment with cytotoxic T lymphocyte-associated antigen-4 (CTLA-4) blockade (ipilimumab)." (PMID 37543576, 2023). "Treatment with a fully human anti-cytotoxic T-lymphocyte–associated protein 4 (CTLA-4) antibody has been associated with long-lasting responses in several hematologic malignancies and a high proportion of durable, complete responses in patients with advanced metastatic melanoma." (PMID 35681659, 2022). "Immune checkpoint inhibitors, such as anti-cytotoxic T Lymphocyte associated protein- 4 (CTLA-4) antibody (Ipilimumab) and anti-PD-L1 antibodies (atezolizumab, druvalumab, and avelumab) have shown some clinical benefits in the treatment of patients with advanced-stage metastatic melanoma." (PMID 32626712, 2020). "Elevated evidences indicated that blocked the cytotoxic T lymphocyte associated protein 4 (CTLA4), and programmed death 1 (PD-1) or its ligand PD-L1 had demonstrated unparalleled therapeutic efficacy in cancers such as non-small cell lung cancer, metastatic melanoma and bladder cancer." (PMID 32850758, 2020).
metastatic melanoma (continued). "This patient with metastatic melanoma developed hypophysitis related to treatment with ipilimumab, and subsequently developed acute left vision loss and waxing and waning vision loss of the right eye consistent with an inflammatory optic neuritis attributed to CTLA-4 blockade." (PMID 27777775, 2016). "Combined anti-PD-1/CTLA-4 blockade using nivolumab and ipilimumab has shown superiority to anti-PD-1 monotherapy in other immunogenic cancers such as metastatic melanoma." (PMID 41231502, 2026). "METHODS: Pre-treatment formalin-fixed, paraffin-embedded metastatic melanoma specimens from 45 patients treated with anti-PD-1 ± anti-CTLA-4 ICB were included in this study." (PMID 41559679, 2026). "The concurrent inhibition of cytotoxic T-lymphocyte associated protein 4 (CTLA-4) and PD-L1 has demonstrated a synergistic effect in metastatic melanoma, enhancing efficacy Compared to mono therapeutic approaches." (PMID 41431358, 2026). "We analyzed γδ T cells derived from PBMCs of patients with stage IV metastatic melanoma before starting either α-PD-1 monotherapy (pembrolizumab) or α-PD-1/α-CTLA-4 (nivolumab/ipilimumab) combination therapy." (PMID 41310392, 2026). "Our patient is a 71-year-old male with BRAF wild-type metastatic melanoma who was diagnosed with a rare irAE after being treated with PD-1 and CTLA-4 immunotherapy." (PMID 40751168, 2025). "For Stage IV metastatic melanoma, systemic immunotherapy (PD-1 monotherapy or PD-1/CTLA-4 combination) is first-line." (PMID 40978828, 2025). "Immunotherapy, especially PD-1 inhibitors and CTLA-4 inhibitors, is now fundamental in treating metastatic melanoma, enhancing survival rates even in advanced stages." (PMID 40520839, 2025). "Combined checkpoint inhibition with nivolumab (PD-1 inhibitor) and ipilimumab (CTLA-4 inhibitor) in metastatic melanoma has been extensively studied in multiple clinical trials." (PMID 41159031, 2025). "Ipilimumab, a cytotoxic T-lymphocyte-associated antigen-4 (CTLA-4) inhibitor, has been approved by the US Food and Drug Administration to treat unresectable or metastatic melanoma." (PMID 40741211, 2025). "Another essential gene to consider is CTLA-4, which has been linked to the development of pulmonary and cutaneous sarcoidosis in patients treated with anti-CTLA-4 and anti-PD-L1 therapies for metastatic melanoma." (PMID 41026325, 2025). "The fecal microbiome was analyzed in patients with metastatic melanoma before and after ipilimumab (anti-CTLA-4) treatment." (PMID 40927726, 2025). "The research data of KEYNOTE-006 also acknowledged the higher security of ICIs than CTLA-4; therefore, ICIs were more widely used in metastatic melanoma." (PMID 40917780, 2025). "Patients with metastatic melanoma can be treated with immunotherapy using either an anti-PD-1 antibody alone or in combination with an anti-CTLA-4 antibody." (PMID 40148586, 2025). "Immunotherapy with anti-programmed cell death 1 (anti-PD-1) therapy alone or in combination with anti-cytotoxic T lymphocyte antigen-4 (CTLA-4) antibody ipilimumab is currently established as first line for patients with metastatic melanoma." (PMID 39941835, 2025). "This surge of interest began with the discovery that the Cytotoxic T-lymphocyte Antigen (CTLA-4) blocking antibody, ipilimumab, improved overall survival in patients with metastatic melanoma." (PMID 40296914, 2025). "It has been demonstrated that CTLA4 and PD-1, along with its ligand PD-L1, have demonstrated significant therapeutic efficacy in cancers, including non-small cell lung cancer, metastatic melanoma, and bladder cancer." (PMID 39857769, 2025). "Immune checkpoint inhibitors (ICIs), such as anti-Cytotoxic T-Lymphocyte Antigen 4(CTLA-4) and anti-Programmed cell death protein 1 (PD-1) agents, have improved the prognosis of patients with metastatic melanoma." (PMID 40211360, 2025).
metastatic melanoma (continued). "The first immune checkpoint inhibitor to receive approval in 2011 was the anti-CTLA-4 antibody ipilimumab for the treatment of unresectable or metastatic melanoma." (PMID 40641936, 2025). "Ipilimumab, a cytotoxic T-lymphocyte-associated protein 4 (CTLA-4) blocking antibody, approved by the FDA in 2011, demonstrates prolonged survival in patients with metastatic melanoma." (PMID 39941158, 2025). "In this case, a patient with metastatic melanoma treated with combined CTLA-4 and PD-1 blockade developed progressive left hip pain, with imaging findings suggestive of osteonecrosis of the femoral head." (PMID 41229492, 2025). "Another study reviewed 16 clinical trials that combined the CTLA-4 inhibitor ipilimumab and radiation therapy for metastatic melanoma patients and reported an abscopal effect in 26.5% of patients." (PMID 39902234, 2025). "Here, we present the case of a patient with metastatic melanoma treated with combined anti-CTLA-4 and anti-PD-1 therapy, who developed a femoral head lesion initially suggestive of osteonecrosis on imaging." (PMID 41229492, 2025). "We examined the publicly accessible scRNA-seq data of 48 tumor biopsy samples obtained either pre- or post-treatment from patients (n = 32) with metastatic melanoma treated with anti-PD1 (n = 24) or anti-PD1+anti-CTLA4 (n = 8), as published." (PMID 38451948, 2024). "All studies investigating irAEs resulting from anti-CTLA-4 therapy were performed with patients with advanced or metastatic malignant melanoma." (PMID 38539558, 2024). "The introduction of ICIs, such as PD-1, PD-L1, and CTLA-4 inhibitors, has revolutionized the clinical management of metastatic melanoma (MM)." (PMID 39408929, 2024). "The overall patient response to ICI is heterogeneous with most cancer types showing response rates ranging from 15% to 40%, based on the tumour type, while CTLA‐4 therapy delivers an objective response rate of 20% in metastatic melanoma patients." (PMID 38963257, 2024). "With the recent approval of anti-LAG-3 for the treatment of late-stage metastatic melanoma, identification of biomarkers that can inform on prescription of monotherapy anti-PD-1, versus combinations that include anti-CTLA-4 and LAG-3, are urgently needed." (PMID 38217840, 2024). "A study involving 195 metastatic malignant melanoma patients observed prolonged OS in patients who received immunotherapy (IL-2, anti-PD-1, or anti-CTLA-4) and were taking pan beta blockers experienced." (PMID 38850359, 2024). "The recent combined immune checkpoint (ICI) inhibition therapy with Ipilimumab (a CTLA-4 blocking agent) and Nivolumab (a PD-1 blocking agent) demonstrated better anticancer outcomes in advanced or metastatic melanoma compared to monotherapy regimen." (PMID 38322766, 2024). "It was reported that Th17 cells were increased after CTLA-4 blockade in patients with metastatic melanoma." (PMID 38539560, 2024). "In this single-centre, retrospective cohort study, we examined medical records and laboratory data of 197 consecutive patients treated with combined CTLA-4 and PD-1 inhibition (ipilimumab; ipi + nivolumab; nivo) for metastatic melanoma or renal cell carcinoma." (PMID 38171113, 2024). "In March 2011, the U.S. Food and Drug Administration (FDA) approved ipilimumab, a cytotoxic T-lymphocyte associated protein 4 (CTLA-4) inhibitor, as the first immune checkpoint inhibitor (ICI) for treating metastatic melanoma." (PMID 39534873, 2024). "A phase 1 clinical trial reported an ORR of 19.6% for metastatic melanoma patients treated with ipilimumab, an anti-CTLA-4 antibody, in combination with the angiogenesis inhibitor bevacizumab." (PMID 39040456, 2024). "Recent studies have shown that VISTA expression has increased after PD1 blockage in metastatic melanoma and CTLA4 in prostate cancer." (PMID 38634058, 2024). "Ipilimumab, a mAb functioning as a CTLA-4 inhibitor, was initially approved for treating metastatic melanoma in 2011." (PMID 38791528, 2024).